SNORD59A (small nucleolar RNA, C/D box 59A)
Synonyms: U59; RNU59
Gene: Small nucleolar RNA gene on chromosome 12 (56,645,027 to 56,645,101, reverse strand). Ensembl gene ENSG00000207031.
Gene Ontology:
Biological process: RNA processing
Cellular component: nucleolus
Homologues: Orthologues: chimpanzee SNORD59A (100% identical), macaque SNORD59A (96% identical), pig SNORD59A (95% identical), guinea pig SNORD59A (92% identical), rabbit SNORD59A (92% identical), rat Snord59a (91% identical), mouse Snord59a (85% identical).